BTK (Bruton tyrosine kinase)
Diseases named in the same sentence as BTK in open-access papers (continued):
Sharing a sentence is not in itself a finding about the gene and the disease.
B-cell lymphomas (continued). "The Bruton tyrosine kinase inhibitor ibrutinib, given as monotherapy or combined with other molecules, has proven effective in numerous B-cell lymphomas." (PMID 35406532, 2022). "Our work demonstrated that ASK120067 exhibited significant anti-tumour activities against B-cell lymphoma and T-cell leukemia in vivo and in vitro, via targeting BTK and ITK." (PMID 36588692, 2022). "In terms of R/R B-cell NHL management, BTK inhibitors provide an opportunity to start a chemotherapy-free era as novel agents." (PMID 36275715, 2022). "Ibrutinib, also known as PCI-32765, was the first BTK inhibitor approved and tested in clinical trials for patients with B cell lymphomas." (PMID 34063667, 2021). "BTK inhibitors (BTKis) are new drugs in B cell lymphoma, which have been used in newly diagnosed relapse/refractory (R/R) or rituximab-resistant DLBCL." (PMID 33827598, 2021). "B-cell NHLs rely on Bruton’s tyrosine kinase (BTK) mediated B-cell receptor signaling for survival and disease progression." (PMID 33946867, 2021). "Activated B-cell lymphoma pathogenesis exhibits irregular initiation of the BTK–mediated B-cell receptor signaling pathway based on the genetic mutation in the BCR signaling pathways." (PMID 33946867, 2021). "BTK inhibitors (BTKis) ibrutinib and acalabrutinib are important new drugs for the treatment of B-cell lymphoma including DLBCL in recent 10 years." (PMID 33827598, 2021). "Comparative analysis among canine B- and T-lymphoid cell lines and primary B-cell lymphoma samples, reveals potentially high-impact variants in PI3K and BTK." (PMID 34884478, 2021). "In 2015, another member of the TEC family, BTK has been shown to be an effective biomarker for Hodgkin and B cell non-Hodgkin lymphoma." (PMID 34899868, 2021). "In this study, our results revealed that SY-1530, a novel BTK inhibitor, has significant inhibitory activity in mouse xenograft models and spontaneous canine B-cell lymphoma." (PMID 34264564, 2021). "Starting from these studies, the same authors synthesized a large library of compounds with very potent action on B-cell lymphomas (Ramos and Jeko-1) and Daudi cell lines with high BTK expression." (PMID 34885993, 2021). "Ibrutinib, the first-generation BTK inhibitor, has shown excellent antitumor activity in both indolent and aggressive B-cell lymphoma." (PMID 33005100, 2020). "Meanwhile, these data suggest that further studies are needed to determine how genetic and tumor microenvironment factors, alone or in combination, create intrinsic BTK dependence in different B-cell lymphoma." (PMID 33005100, 2020). "BTK is a central contributor to B-cell lymphoma pathogenesis, as it is significantly more active (increased phosphorylation) in B-cell lymphomas than in normal B-cells." (PMID 32455989, 2020). "Ibrutinib, a Bruton’s tyrosine kinase (BTK) inhibitor, effectively treats various hematologic malignancies including many B-cell lymphomas, but atrial fibrillation can occur in 4–16% of patients on ibrutinib." (PMID 33322622, 2020). "Bruton’s tyrosine kinase (BTK) is overexpressed in many subtypes of B-cell lymphoma as a downstream kinase in the BCR signaling pathway." (PMID 33005100, 2020). "Bruton's tyrosine kinase (BTK) inhibitors which are approved for treatment of B cell lymphomas have the capacity to block both BCR signaling and STAT3 activation and are capable of reducing IL-10 production and PD-L1 expression in B cells." (PMID 32425944, 2020). "Chronic activation of B-cell receptor (BCR) signaling via Bruton tyrosine kinase (BTK) is largely considered to be one of the primary mechanisms driving disease progression in B–Cell lymphomas." (PMID 32455989, 2020). "Ibrutinib, the first generation of BTK inhibitor, has shown excellent antitumor activity in both indolent and aggressive B-cell lymphoma." (PMID 33005100, 2020).
B-cell lymphomas (continued). "BTK is a vital component of BCR signaling, and targeting BTK is clinically efficacious in several hematologic malignancies, including B-cell lymphomas." (PMID 27434128, 2016). "Combining PI with the pan B-cell-directed Bruton tyrosine kinase inhibitor ibrutinib appears a natural option for future improved treatment of multiple myeloma (MM) and B-cell lymphomas." (PMID 26099967, 2015). "This review discussed in details the role of BTK in B-cell signaling, molecular interactions between B cell lymphoma/leukemia cells and their microenvironment." (PMID 24472371, 2014). "Orally administered, the BTK inhibitor induced significant objective responses in patients with B-cell NHL or CLL." (PMID 23967355, 2013). "When orally administered to mice with collagen-induced arthritis it reduced the level of circulating antibodies suppressing disease and in dogs with spontaneous B cell non-Hodgkin lymphoma (NHL) treatment with the BTK inhibitor induced clinical responses." (PMID 23967355, 2013). "BTK, a tyrosine kinase enzyme, is an attractive drug target and inhibitors are already being developed against it for a number of diseases like B-cell lymphomas and some autoimmune disorders." (PMID 22479409, 2012). "Ramos cell line (B cell lymphoma) was chosen due to its high expression of the target protein BTK." (PMID 41027871, 2025). "Notably, BTK, AKT, and PI3K are well-established targets implicated in B-cell lymphoma and leukemia, while MYC is also a key oncogene associated with these diseases." (PMID 40235547, 2025). "Understanding BTK’s dual roles unveils opportunities for therapeutics targeting its scaffolding function, promising advancements in disrupting lymphomagenesis and refining B cell lymphoma treatments." (PMID 39062757, 2024). "Theoretically, the combination of a BTK inhibitor with rituximab and lenalidomide may be an effective regimen for R/R B-cell NHL." (PMID 38555311, 2024). "The first BTK inhibitor approved for use in the clinic was Ibrutinib; a small molecule initially described as a high affinity BTK inhibitor and subsequently shown to be effective in animal models of autoimmune disease and B-cell lymphoma." (PMID 37651403, 2023). "However, BTK inhibition in B-cell lymphomas rarely results in a complete response and most patients experience eventual disease relapse." (PMID 37954584, 2023). "Downstream in this process, BTK remains consistently active in B cell lymphomas." (PMID 37745115, 2023). "The introduction of inhibitors of phosphatidylinositol 3-kinase (PI3K) and Bruton tyrosine kinase (BTK) has represented a big step forward in the treatment of patients affected by indolent B cell lymphomas, including marginal zone lymphoma (MZL) and lymphoplasmacytic lymphoma (LPL)." (PMID 36675328, 2023). "Persistent survival signaling though downstream molecules such as interleukin 1 receptor-associated kinase 4 (IRAK-4), an integral part of the “myddosome” complex, has been shown to be constitutively active in B-cell lymphoma patients treated with BTK inhibitors." (PMID 37954584, 2023). "Targeting BTK is therefore an effective strategy for B-cell lymphoma treatment." (PMID 36364276, 2022). "In addition, to examine the selectivity of SY-1530 in cells, we used the Pfeiffer and DOHH2 B-cell lymphoma cell lines, which endogenously express BTK, and the Jurkat T-cell lymphoma cell line, which expresses ITK." (PMID 34264564, 2021). "Dysregulation of BTK signaling in B cells leads to B cell lymphoma." (PMID 34063667, 2021). "BTK inhibitors have also been reported to be effective at treating canine B-cell lymphoma." (PMID 34884478, 2021). "Moreover, the administration of another BTK inhibitor, acalabrutinib, in canine B-cell lymphoma in vitro and in vivo models resulted in dose-dependent inhibition of BTK autophosphorylation and clinical benefit in 30% of the dogs." (PMID 34884478, 2021).
B-cell lymphomas (continued). "Given the role that BTK plays in survival of B-cell lymphomas, the expression of other BTK kinases in this large cancer class may represent an important therapeutic vulnerability." (PMID 34307353, 2021). "Inventing more novel agents with differential mechanisms or synergistically combining BTK inhibitors with other chemotherapy, antibodies, targeted agents, or immunotherapy may open the way for a cure in B-cell lymphomas." (PMID 33122850, 2021). "Due to the involvement of BTK in multiple immunological signaling pathways, there have been a host of inhibitors developed with different binding modes all targeting the kinase domain of BTK as a treatment option for B cell lymphomas and other BTK-reliant diseases." (PMID 34249912, 2021). "The specific role of BTK in B cell lymphomas has been reviewed elsewhere." (PMID 34249912, 2021). "Given the success of the BTK inhibitor ibrutinib in the treatment of B cell lymphoma, the TEC family member ITK has become an appealing target for inhibiting TCR signaling, which plays an important role in T cell activation, development, differentiation, and cytokines production." (PMID 30814910, 2019). "Novel agents targeting B cell signalling pathways, such as, inhibitors of Bruton tyrosine kinase and phosphoinositol-3 kinase, may play important role in the therapy of this rare entity of B cell lymphomas." (PMID 28191314, 2017). "Although there are many subtypes of B lymphomas, an intriguing common feature is that all types of B lymphomas require BCR signals to gain advantages in their tumorigenesis in vivo and the BTK inhibitor has demonstrated clinical benefit for several types of B cell lymphomas." (PMID 29097663, 2017). "Therefore, BTK inhibitors may require an alternative approach for treating aggressive B-cell lymphoma." (PMID 38555311, 2024). "Additionally, as BTK inhibition has been previously shown to synergize with IRAK inhibition, JH-X-119-01 was co-treated with the BTK inhibitor ibrutinib, which showed synergistic tumor cell-killing effects in MYD88-mutated B-cell lymphoma cells." (PMID 38792088, 2024). "In fact, in the context of treating B cell lymphomas, PLCγ2 ibrutinib resistant variants are hyper-sensitive to activation regardless of BTK’s kinase activity suggesting that the kinase-independent functions of BTK might be responsible." (PMID 34249912, 2021). "The patient received a treatment regimen that included acalabrutinib, a selective inhibitor of Bruton’s tyrosine kinase (BTK) commonly used in CLL and B-cell lymphomas." (PMID 41141198, 2025). "In contrast, Bruton’s tyrosine kinase (BTK) serves as a key enzyme in the B-cell receptor (BCR) signaling pathway, which plays a vital role in the survival and proliferation of B-cell lymphomas." (PMID 40616640, 2025). "Potential synergism between Bruton’s tyrosine kinase (BTK) inhibitor and lenalidomide in treating aggressive B-cell lymphoma has been suggested." (PMID 38555311, 2024). "Bruton's tyrosine kinase (BTK) is a key effector molecule in B-cell development and is expressed in B-cell lymphomas." (PMID 37845755, 2023). "Abnormal activation of protein kinases are a common pro-tumorigenic mechanism, and Bruton’s tyrosine kinase (BTK) is one such protein kinase that plays a crucial role in oncogenic signaling, especially in various B cell lymphomas." (PMID 37277776, 2023). "For instance, Bruton’s tyrosine kinase (BTK) and Janus kinase 3 (JAK3) are two validated and therapeutically amenable targets to effectively treat B-cell lymphomas and can be used to develop a dual-target inhibitor." (PMID 37894618, 2023). "Bruton’s tyrosine kinase (BTK) and Janus kinase 3 (JAK3) are popular synergistic targets for B-cell lymphoma." (PMID 37894618, 2023). "Among them are Bruton’s tyrosine kinase (BTK) inhibitors, which have demonstrated excellent efficacy in indolent B-cell NHLs and CLL." (PMID 37185435, 2023).
B-cell lymphomas (continued). "Ibrutinib, a first-generation oral small molecule, is a selective inhibitor of Bruton's Tyrosine Kinase (BTK), a critical component of the B cell receptor (BCR) pathway in B cell lymphomas." (PMID 37745115, 2023). "Non-covalent BTK inhibitors, such as pirtobrutinib, vecabrutinib, and fenebrutinib, which do not bind C481, are reported to have fewer off-target toxicity, thus providing a promising effective option for patients with B-cell lymphoma, especially those with BTK C481 mutations." (PMID 36138486, 2022). "We measured the phosphorylation of BTK and ITK in B-cell lymphoma or T-cell leukemia cell lines treated with increasing doses of ASK120067 using western blotting." (PMID 36588692, 2022). "Inhibition of Bruton’s tyrosine kinase (BTK), an ITK homolog required for antigen-receptor signaling in B cells, has transformed the therapeutic landscape in many B-cell lymphomas." (PMID 36329027, 2022). "Bruton’s tyrosine kinase (BTK) is a key protein from the TEC family and is involved in B-cell lymphoma occurrence and development." (PMID 36364276, 2022). "It demonstrated that acalabrutinib potently inhibited BTK activation, thus inhibiting the proliferation of CLBL1 cells, a canine B-cell lymphoma cell line." (PMID 33122850, 2021). "In CLL and B-cell non-Hodgkin’s lymphoma (NHL), SYK is involved both in Bruton’s Tyrosine Kinase (BTK) pathway activation and IL4-driven resistance to BTK inhibitors, while JAK kinases transduce cytokine signaling, which supports tumor growth." (PMID 33401428, 2021). "Therefore, BTK could be crucial for SYK pro-oncogenic function in B-cell lymphomas." (PMID 33670716, 2021). "Similar design of bi-functional degraders induce degradation of BCR-Abl and Bruton’s tyrosine kinase (BTK), showing therapeutic potentials in the treatment of chronic myeloid leukemia (CML) and B-cell lymphoma, respectively." (PMID 31938543, 2020). "Acalabrutinib is an oral, second-generation BTK inhibitor with a favourable toxicity profile and demonstrated activity in CLL and B-cell lymphomas." (PMID 31109313, 2019). "In these B-cell NHLs with MYD88L265P mutation and even those without, BTK inhibitors such as ibrutinib, acalabrutinib, and zanubrutinib have shown efficacy by virtue of inhibiting BTK’s key role in in BCR and TLR signaling." (PMID 37954584, 2023). "BTK overexpression increases germinal center generation, leading to dysregulated homeostasis of T-cells, thus explaining the pathological role of BTK in influencing BCR signaling in B-cell lymphomas." (PMID 36986499, 2023). "Discussion of all these targets is beyond the scope of this review article, but one class of therapy, small molecular inhibitor of Bruton tyrosine kinase (BTK), an essential component for BCR signaling, has gained a lot of attention in recent years as a treatment for various B-cell lymphomas." (PMID 34888236, 2021). "These suggested that the combination therapy may overcome some mechanisms of resistance in the BTK signaling pathway and supported the clinical investigation of these combinations in patients with CLL and B-cell lymphoma." (PMID 29690649, 2018). "Bruton’s tyrosine kinase (BTK) and phosphoinositide 3-kinase (PI3K) in the B-cell receptor (BCR) signaling pathway are considered potential therapeutic targets for the treatment of B-cell lymphomas, among which, diffuse large B-cell lymphoma (DLBCL) is the most common type." (PMID 34884478, 2021).
B-cell lymphomas (continued). "Although it has been shown that QL47 inhibition of BTK is primarily responsible for this phenotype, our findings described here suggest that the antiproliferative activities of QL47 in B cell lymphoma may additionally be mediated through its effect on translation." (PMID 31914414, 2020).
autoimmune disease (103 papers, 2012 to 2025). A disorder resulting from loss of function or tissue destruction of an organ or multiple organs, arising from humoral or cellular immune responses of the individual to their own tissue constituents. "In general, BTK inhibition causes a block of different downstream cell signaling pathways strictly related to the development of B-cell malignancies, as well as autoimmune diseases by impairing cell proliferation, migration, and the activation of NF-κB." (PMID 38396884, 2024). "Its involvement in B cell survival and differentiation has also linked BTK with autoimmune diseases." (PMID 38698867, 2024). "This implies that in MS alternative mechanisms underlie BTK dysregulation in B cells as compared with primarily antibody-driven autoimmune diseases." (PMID 35852869, 2022). "Initially identified as a mutation in human immunodeficiency X-linked agammaglobulinemia, BTK has been implicated in inflammatory signaling, thereby holding promise as a therapeutic target for numerous autoimmune diseases." (PMID 36521376, 2022). "BTK is a crucial protein in BCR signaling, and increased BTK levels are associated with autoimmune diseases." (PMID 36277750, 2022). "BTK is a signaling kinase that plays a crucial role in the activation of pathogenic B cells and autoantibody production in human autoimmune disorders." (PMID 35628931, 2022). "By exposing the disease-relevant mechanisms involved, this work reveals that BTK inhibition is a therapeutic approach that meets the need for selectively targeting pathogenic B cells in MS and other types inflammatory and autoimmune disorders." (PMID 35852869, 2022). "Btk-deficiency protects against several spontaneous autoimmune diseases in mouse models and clinical trials investigating the efficacy of BTK inhibitors in human autoimmune disease are ongoing." (PMID 35422819, 2022). "Bruton's tyrosine kinase (BTK) has recently become a promising drug target for many diseases, especially haematopoietic malignancies and autoimmune diseases associated with B lymphocytes." (PMID 31312501, 2019). "Human autoimmune disease is also associated with increased BTK expression: we recently showed that patients with RA and SjS have increased BTK protein levels in B cells from peripheral blood, compared with healthy controls." (PMID 30761150, 2019). "Since Bruton’s tyrosine kinase (BTK) is a kinase implicated in autoimmune disorders, BTK inhibition is considered as an attractive approach for the treatment of autoimmune diseases such as rheumatoid arthritis." (PMID 31216762, 2019). "Because of the important role of BTK in regulating key pathogenic pathways, BTK inhibitors are under investigation as treatment options for various autoimmune diseases, including RA." (PMID 28742141, 2017). "Our results clearly suggest a similar scenario for XLA patients, who experience autoimmune disease and BTK deficient monocytes are known to be pro-inflammatory." (PMID 26417435, 2015). "Reductions in cytokines like IL-1β, IL-6, IL-12, and IL-17 caused by BTK inhibitiors in some primary autoimmune diseases may suggests possible mechanism to abrogate iRAEs." (PMID 37081866, 2023). "Inhibition of BTK hyperactivity is implicated in B-cell malignancies and autoimmune diseases." (PMID 36986499, 2023). "Recent studies reveal that BTK expression is implicated in numerous autoimmune diseases." (PMID 36521376, 2022). "Together, these findings reveal multiple pathogenic roles of BTK in autoimmune diseases." (PMID 34778053, 2021). "In autoimmune diseases such as RA, the overexpression of pre-B cell receptor and overactivation of FcR signaling pathways have been linked to the induction of autoantibodies, making BTK a potential target for RA." (PMID 33802091, 2021). "Therefore, BTK inhibition causes a block of different down-stream cell signalling pathways strictly related to the development of B-cell malignancies, as well as autoimmune diseases." (PMID 34885993, 2021).